MESP1 (mesoderm posterior bHLH transcription factor 1)
Description:
Transcription factor. Plays a role in the epithelialization of somitic mesoderm and in the development of cardiac mesoderm. Defines the rostrocaudal patterning of the somites by participating in distinct Notch pathways (By similarity).
Synonyms: bHLHc5; MGC10676
Tractability: No criterion of Open Targets' tractability assessment is met for any kind of drug.
Gene: Protein-coding gene on chromosome 15 (89,749,875 to 89,751,249, reverse strand). Ensembl gene ENSG00000166823.
Subcellular location: Nucleus
Subcellular location (Human Protein Atlas): Nucleoplasm; Nucleoli
Pathways (Reactome):
Developmental Biology: Cardiogenesis
Gene Ontology:
Molecular function: DNA-binding transcription factor activity; protein binding; transcription cis-regulatory region binding; DNA-binding transcription factor activity, RNA polymerase II-specific; RNA polymerase II cis-regulatory region sequence-specific DNA binding; cis-regulatory region sequence-specific DNA binding; DNA-binding transcription activator activity, RNA polymerase II-specific; protein dimerization activity; sequence-specific double-stranded DNA binding
Biological process: cardiac atrium formation; cardiac muscle cell differentiation; cardiac vascular smooth muscle cell differentiation; cardiac ventricle formation; endothelial cell differentiation; neurogenesis; positive regulation of transcription by RNA polymerase II; sinoatrial node cell differentiation; cardiac cell fate determination; cardioblast anterior-lateral migration; cardioblast migration to the midline involved in heart field formation; embryonic heart tube morphogenesis; gastrulation; growth involved in heart morphogenesis; heart induction; heart looping; heart morphogenesis; lateral mesoderm development; mesoderm formation; negative regulation of canonical Wnt signaling pathway; negative regulation of DNA-templated transcription; negative regulation of endodermal cell fate specification; negative regulation of mesodermal cell fate specification; positive regulation of DNA-templated transcription; positive regulation of hepatocyte differentiation; and 6 more
Cellular component: nucleoplasm; chromatin; nucleus
Genetic constraint (gnomAD): Loss-of-function variants: 27 observed, 11.49 expected, observed/expected ratio (o/e) 2.35. The synonymous counts are far from expectation, so gnomAD's model fits this gene poorly and the ratio says little. Missense variants: 484 observed, 275.95 expected, observed/expected ratio (o/e) 1.75, 90% interval 1.63 to 1.89. Synonymous variants: 216 observed, 122.64 expected, observed/expected ratio (o/e) 1.76, 90% interval 1.57 to 1.94.
Gene-disease validity (ClinGen):
ClinGen rates the evidence that MESP1 causes each of these diseases.
congenital heart disease (autosomal dominant): Moderate. A heart disease that is present at birth.
Homologues: Orthologues: chimpanzee MESP1 (99% identical), macaque MESP1 (92% identical), pig MESP1 (74% identical), dog MESP1 (73% identical), mouse Mesp1 (59% identical), rat Mesp1 (58% identical), tropical clawed frog mespb (28% identical), zebrafish mespbb (27% identical), tropical clawed frog mespa (25% identical), zebrafish mespab (24% identical), zebrafish mespba (24% identical), zebrafish mespaa (21% identical), and 1 more. Paralogues in human: MESP2 (59% identical), MSGN1 (19% identical).
Diseases named in the same sentence as MESP1 in open-access papers:
MESP1 is named in the same sentence as 22 diseases in open-access papers, as found by Europe PMC text mining. Sharing a sentence is not in itself a finding about the gene and the disease. The quoted sentences say what the papers report.
myocardial infarction (4 papers, 2016 to 2025). Gross necrosis of the myocardium, as a result of interruption of the blood supply to the area, as in coronary thrombosis. "We performed transcriptome and functional analysis of human MESP1+ cardiovascular progenitor cells and tested their therapeutic potential using a rat model of myocardial infarction." (PMID 32550911, 2020). "In a blinded study, day 5 Mesp1-CPCs were injected into the intramyocardial tissue within the infarct and border zone areas, immediately following myocardial infarction (MI) induction by left anterior descending artery (LAD) ligation." (PMID 27538477, 2016). "ISL1+ MESP1+ FOXA2+ stem cell clones isolated from neonatal cardiovascular tissue represent a novel resource of cells with the capacity to restore cardiac function following myocardial infarction in a preclinical large animal model." (PMID 41561127, 2025). "Moreover, upon engraftment into the rat model of myocardial infarction (MI), MESP1+ cells differentiated to ECs and CMs, and significantly improved heart function." (PMID 32550911, 2020). "Finally, we showed that the engraftment of MESP1+ cells repaired rat myocardial infarction model." (PMID 32550911, 2020). "Comparable ISL1+ MESP1+ FOXA2+ stem cell clones were then isolated from sheep for functional analysis in a sheep model of myocardial infarction and allogeneic stem cell-based repair without immunosuppression." (PMID 41561127, 2025).
cardiac hypertrophy (2 papers, 2022 to 2025). "Consistent with the RNAseq data from young Prdm16flox/flox; Mesp1-Cre mice, we confirmed that many genes that are implicated in cardiac hypertrophy and oxidative stress were upregulated or downregulated in the cardiac tissues of 1-month-old, male Prdm16CKO compared with control." (PMID 35862303, 2022). "Surprisingly, deletion of Prdm16 at the earliest time point of cardiac development, using a constitutive Mesp1-Cre driver (Prdm16CMKO-Mesp1), only resulted in cardiac hypertrophy in late adulthood." (PMID 40439125, 2025). "It appears that our strain (5-month-old Prdm16flox/flox; Myh6-Cre) progresses to cardiac hypertrophy earlier than 9-month-old Prdm16flox/flox; Mesp1-Cre mice, consistent with the other conditional strain (Prdm16flox/flox; αMHCMerCreMer/+) developing cardiac hypertrophy as early as age 3 months." (PMID 35862303, 2022).
ischemia (2 papers, 2017 to 2020). A hypoperfusion of the BLOOD through an organ or tissue caused by a PATHOLOGIC CONSTRICTION or obstruction of its BLOOD VESSELS, or an absence of BLOOD CIRCULATION. "To explore the reparatory potential of human MESP1+ cells in vivo, we used a rat model of MI, where the left anterior descending coronary artery (LAD) was ligated to induce ischemia and CM death." (PMID 32550911, 2020). "To evaluate the therapeutic potential of ECs derived from MESP1+ cells, we employed a critical limb ischemia (CLI) mouse model where the ischemia was induced by ligation of the left femoral artery." (PMID 28114972, 2017).
ischemic disease (2 papers, 2016 to 2017). Lack of blood supply to an area of the body, resulting in impairment of tissue oxygenation. "Studying the biology of Mesp1-CPCs in cell culture and ischemic disease models is an important initial step toward using them for heart disease treatment." (PMID 27538477, 2016). "Thus MESP1+ cell-derived ECs could be a potentially useful cell source for blood vessel regeneration and the treatment of ischemic diseases." (PMID 28114972, 2017).
atrial septal defect (1 paper, 2016). Interauricular communication is a congenital malformation characterized by a communication between the atrial chambers of the heart. "Mesp1 conditionally mutant Hira embryos presented with generalised oedema and cardiac malformations such as ventricular septal defect (VSD), atrial septal defect (ASD), thin ventricular wall and constricted pulmonary trunk (PT)." (PMID 27518902, 2016).
brain hemorrhage (1 paper, 2023). "We could not examine Mesp1-Cre;Lmx1bfl/fl mutants at postnatal stages because the newborns were visibly in distress with brain hemorrhage and thus had to be euthanized." (PMID 37593235, 2023).
dilated cardiomyopathy (1 paper, 2023). Cardiomyopathy which is characterized by dilation and contractile dysfunction of the left and right ventricles. "In the CardiacMeso-fated segment, Myl7 and Id2 were reduced relative to controls, as was Ankrd1, a gene implicated in sarcomere-binding and dilated cardiomyopathy that is known to be upregulated with overexpression of Mesp1." (PMID 36994838, 2023).
limb ischemia (1 paper, 2017). A ischemia that involves the limb. "Finally, we performed cell transplantation into a critical limb ischemia mouse model to test the repairing potential of endothelial-primed MESP1+ cells." (PMID 28114972, 2017).
pancreatic cancer (1 paper, 2025). "The RNA-seq underscore the pivotal role of MESP1 in diverse cellular physiological mechanisms and cancer pathways, establishing it as a vital regulator of pancreatic cancer progression with substantial implications for research and therapeutic strategies." (PMID 40610403, 2025).
teratoma (1 paper, 2017). A non-seminomatous germ cell tumor characterized by the presence of various tissues which correspond to the different germinal layers (endoderm, mesoderm, and ectoderm). "Undifferentiated MESP1-mTomato reporter cells formed teratoma after subcutaneous injection to the groin region of immune-deficient mice, while differentiated MESP1+ cells did not form any teratoma after 8 weeks." (PMID 28114972, 2017).
cancer (5 papers, 2018 to 2025). A tumor composed of atypical neoplastic, often pleomorphic cells that invade other tissues. "RNA-seq of silencing MESP1 indicated that MESP1 was linked to multiple cancer-associated pathways, including TNF, JAK-STAT, Wnt, and Hippo pathways." (PMID 40610403, 2025). "It is evident that MESP1 may interact with DNA to regulate oncogene transcription within the nucleus, and may directly associate with cancer-related proteins to modulate their functions in the cytoplasm." (PMID 40610403, 2025). "As a transcription factor, MESP1 possesses the ability to bind directly to DNA, thereby modifying the expression of numerous genes that are integral to cell adhesion, migration, and other cancer-associated traits, thus contributing to tumorigenesis and development." (PMID 40610403, 2025). "Importantly, MESP1 has also been connected to various cancer metabolism pathways, such as MAPK, PI3K-AKT, and carbon metabolism." (PMID 40610403, 2025). "Consequently, MESP1 is likely positioned as a target molecule for specific natural metabolites, influencing downstream proteins and cancer progression." (PMID 40610403, 2025). "MESP1 is a pivotal protein through which DML exerts its anti-cancer effects by regulating H3K18la." (PMID 40610403, 2025). "Subsequently, western blot analyses revealed that the downregulation of MESP1 expression led to an increase in Bax protein levels, a decrease in Bcl2 protein levels, enhanced cancer cell apoptosis rate, suppression of EMT, and a reduction in metastasis of PC cells." (PMID 40610403, 2025). "The results indicated that, in comparison to the other candidate genes, the mRNA expression of MESP1 was markedly downregulated by DML, while it showed elevated expression in cancer cells." (PMID 40610403, 2025). "We also note that transcription factor motif enrichment analysis of the cancer-specific enhancers revealed FOXA1, MESP1/2, and TFAP2C as the top three transcription factors enriched at these enhancers based on adjusted p-value." (PMID 37685859, 2023).
tumor (2 papers, 2018 to 2025). "Immunohistochemical evaluations additionally demonstrated that in comparison to the sh-NC group, the sh-MESP1 group displayed a diminished expression of Ki67 and a decrease in tumor proliferation." (PMID 40610403, 2025).
heart disease (1 paper, 2016). "Here, to characterize further specification of these Mesp1-EYFP+ cells, we investigated their contribution to multiple lineages in ES cell differentiation (in vitro characterization) and heart disease (in vivo characterization)." (PMID 27538477, 2016). "How the progeny of Mesp1-expressing cells contribute to multiple lineages in ES cell differentiation and heart diseases has not been explored, due to the transitory nature of its expression." (PMID 27538477, 2016).
infection (1 paper, 2021). The state of being infected such as from the introduction of a foreign agent such as serum, vaccine, antigenic substance or organism. "After 18 days (starting from SKO infection/transfection) of reprogramming, the mRNA levels of cardiac progenitor marker Mesp1, Isl1 and Nkx2.5 were significantly upregulated in the group with mRNA approach when comparing with the retrovirus approach." (PMID 33942933, 2021).
MESP1 also shares sentences with these, for which no sentence is quoted: breast carcinoma (1 paper); CHARGE syndrome (1); hepatocellular carcinoma (1); hypertrophic cardiomyopathy (1); mastitis (1); scoliosis (1); ventricular septal defect (1); Wilms tumor (1).